TRAV12-2 (T cell receptor alpha variable 12-2)
Description:
V region of the variable domain of T cell receptor (TR) alpha chain that participates in the antigen recognition. Alpha-beta T cell receptors are antigen specific receptors which are essential to the immune response and are present on the cell surface of T lymphocytes. Recognize peptide-major histocompatibility (MH) (pMH) complexes that are displayed by antigen presenting cells (APC), a prerequisite for efficient T cell adaptive immunity against pathogens. Binding of alpha-beta TR to pMH complex initiates TR-CD3 clustering on the cell surface and intracellular activation of LCK that phosphorylates the ITAM motifs of CD3G, CD3D, CD3E and CD247 enabling the recruitment of ZAP70. In turn ZAP70 phosphorylates LAT, which recruits numerous signaling molecules to form the LAT signalosome. The LAT signalosome propagates signal branching to three major signaling pathways, the calcium, the mitogen-activated protein kinase (MAPK) kinase and the nuclear factor NF-kappa-B (NF-kB) pathways, leading to the mobilization of transcription factors that are critical for gene expression and essential for T cell growth and differentiation. The T cell repertoire is generated in the thymus, by V-(D)-J rearrangement. This repertoire is then shaped by intrathymic selection events to generate a peripheral T cell pool of self-MH restricted, non-autoaggressive T cells. Post-thymic interaction of alpha-beta TR with the pMH complexes shapes TR structural and functional avidity.
Synonyms: TCRAV12S2; TCRAV2S1; TRAV122
Gene: T-cell receptor variable (V) gene on chromosome 14 (21,887,857 to 21,888,502, forward strand). Ensembl gene ENSG00000211789.
Subcellular location: Cell membrane
Gene Ontology:
Molecular function: peptide antigen binding
Cellular component: plasma membrane
Homologues: Orthologues: macaque TRAV12-2 (68% identical), mouse Trav7-1 (68% identical), mouse Trav7-3 (68% identical), mouse Trav7d-3 (68% identical), mouse Trav7n-4 (68% identical), mouse Trav7d-4 (67% identical), mouse Trav7-4 (66% identical), mouse Trav7-2 (65% identical), mouse Trav7d-2 (65% identical), mouse Trav7d-5 (63% identical), mouse Trav7n-5 (63% identical), rat Trav12-3 (63% identical), and 4 more. Paralogues in human: TRAV12-3 (79% identical), TRAV12-1 (74% identical), TRAV29DV5 (45% identical), TRAV23DV6 (42% identical).
Diseases named in the same sentence as TRAV12-2 in open-access papers:
TRAV12-2 is named in the same sentence as 6 diseases in open-access papers, as found by Europe PMC text mining. Sharing a sentence is not in itself a finding about the gene and the disease. The quoted sentences say what the papers report.
melanoma (1 paper, 2025). A malignant, usually aggressive tumor composed of atypical, neoplastic melanocytes. "Given that Melan-A is one of the most common melanoma associated antigens, these results suggest that germline determined TRAV12-2 usage may play a role in anti-melanoma immunity." (PMID 40712021, 2025).
streptococcal infection (1 paper, 2016). Any of the several infectious disorders caused by members of streptococcus, a genus of gram positive bacteria belonging to the family Streptococcaceae. "We hypothesize that MR1-restricted T cells expressing TRAV12-2+ or other atypical TCRs selectively expand at tissue sites, such as the human mouth, tonsils and skin, associated with streptococcal infection." (PMID 27527800, 2016).
infection (1 paper, 2016). The state of being infected such as from the introduction of a foreign agent such as serum, vaccine, antigenic substance or organism. "This unique detection pattern of infection and ligand recognition by TRAV12-2+ D462-E4 compared with TRAV1-2+ MAIT cells indicates a greater diversity in microbial MR1 ligands." (PMID 27527800, 2016). "In contrast to TRAV1-2+ MAIT cells, this TRAV12-2-expressing clone displays a distinct pattern of microbial recognition by detecting infection with the riboflavin auxotroph Streptococcus pyogenes." (PMID 27527800, 2016). "The TRAV12-2+ T-cell clone responded over a range of S. pyogenes MOI in DCs, while the TRAV1-2+ clone did not respond to this infection." (PMID 27527800, 2016).
TRAV12-2 also shares sentences with these, for which no sentence is quoted: Myelopathy (1 paper); schizophrenia (1); tropical spastic paraparesis (1).